IL11 (interleukin 11)
Diseases named in the same sentence as IL11 in open-access papers (continued):
Sharing a sentence is not in itself a finding about the gene and the disease.
breast cancer (continued). "Furthermore, we detected the effect of IL-11 on cisplatin-resistance of breast cancer cells (MBA-MD-231 cells) and esophageal cancer cells (ECA109 cells)." (PMID 27922075, 2016). "miR-379 is expressed in breast cancer, regulating interleukin-11 and Cyclin B1." (PMID 25405349, 2014). "In addition, transcription factors known as tumor suppressors or genes related to breast cancer including c-FOS, EGR1, ID2 and SERPINB2, as well as suppression of metastasis associated genes (CD44 and IL11) have emerged as molecular targets of BSP knockdown." (PMID 24980816, 2014). "Similarly, SMAD4 shifts from its tumor suppressor role to an aggressiveness factor in a mouse model of breast cancer by promoting bone metastasis through TGF-β-activated expression of IL-11." (PMID 24708576, 2014). "Therefore, our work has led to a better understanding of the action of IL-11 in breast cancer-induced osteolysis." (PMID 23311882, 2013). "Moreover, a neutralizing anti-IL-11 antibody significantly inhibited the ability of breast cancer conditioned media to promote the development and/or survival of osteoclast progenitor cells." (PMID 23311882, 2013). "This suggests that some breast cancers may increase the extent of osteoclastogenesis by augmenting the pool of osteoclast progenitor cells via tumor-derived IL-11." (PMID 23311882, 2013). "Moreover, human breast cancer tumors expressing IL-11 have higher rates of bone metastasis occurrences." (PMID 23311882, 2013). "Next, we examined whether recombinant IL-11 is able to replicate the results seen with breast cancer conditioned media." (PMID 23311882, 2013). "Finally, bone marrow flushes cultured in 20% MDA-MB-231 breast cancer conditioned media were subjected to the IL-11 neutralizing antibody (5ug/ml)." (PMID 23311882, 2013). "Importantly, the ability of the breast cancer conditioned media to generate a population of osteoclast progenitor cells was significantly inhibited by a neutralizing anti-IL-11 antibody." (PMID 23311882, 2013). "Given that previous studies showed that human breast cancer cell line MDA-MB-231 expresses IL-11, we investigated whether MDA-MB-231 conditioned media are able to promote the development and/or survival of osteoclast progenitor cells in the whole bone marrow." (PMID 23311882, 2013). "Moreover, we show that MDA-MB-231 breast cancer cells are able to stimulate the development and/or survival of osteoclast progenitor cells and IL-11 is the predominant factor derived from MDA-MB-231 cells that is responsible." (PMID 23311882, 2013). "In the bone microenvironment, TGF-β is released from bone during bone resorption and it stimulates breast cancer cells to produce osteolytic factors, such as interleukin 11 (IL-11), that mediate osteolysis by stimulating osteoclast formation and bone resorption activity." (PMID 22629385, 2012). "It has been suggested that CTGF along with Interleukin 11 might influence cancer metastasis to the bone in breast cancer." (PMID 22028892, 2011). "Likewise, a 1-h pre-treatment with MG132 attenuated TGF-β-induced IL-11 and PTHrP expression in 1205Lu cells (respectively), two known SMAD genes targets implicated in melanoma and breast cancer metastasis to bone." (PMID 21211030, 2011). "Breast cancers that metastasize to bone secrete factors, such as parathyroid hormone-related protein (PTHrP) and interleukin-11 (IL-11), that stimulate osteoclastic bone destruction and the release and activation of growth factors immobilized in the bone matrix." (PMID 19727403, 2009). "This receptor cross-talk activates interleukin-11 (IL-11) expression and function, promoting the expression of pro-tumorigenic genes such as ITGA5 and ICAM-1, and enhancing the migratory and invasive features of patient-derived breast cancer-associated fibroblasts (CAFs)." (PMID 40641933, 2025).
breast cancer (continued). "Over the last few decades, IL-11 signalling has been recognised as a key pro-tumourigenic molecule, with evidence of its importance in the progression of several cancers, including non-small cell lung cancer, pancreatic cancer, renal cell carcinoma, and breast cancer." (PMID 38248304, 2024). "Importantly, a fragment of the intracellular domain of HER2, termed 611-CTF (carboxy terminal fragment), can constitutively homodimerize and regulate MET, EPHA2, matrix metalloproteinase 1, interleukin 11, angiopoietin-like 4, and different integrins, promoting mammary tumor growth and metastasis." (PMID 37138747, 2023). "As it has been demonstrated that the MKL1-SRF/IL-11 signaling is essential for miR-206 function in regulating breast cancer stem cells and tumorigenesis, analyzing this pathway may lead to innovative drug development to control cancer growth and prevent metastasis." (PMID 35163731, 2022). "Targeting MKL1/IL-11 pathway, miR-206 could suppress breast cancer stemness and metastasis." (PMID 34345203, 2021). "Overall, these findings suggest that dysregulation of the miR-124/IL-11 axis affects tumor-stromal interactions during the bone metastasis of breast cancer, thus exerting a negative influence on clinicopathological characteristics and the survival of breast cancer patients with bone metastasis." (PMID 29343249, 2018). "Therefore, inhibiting IL-11 signaling might be a promising therapeutic opportunity to treat bone metastases from breast cancer." (PMID 29343249, 2018). "Importantly, in vivo assay showed that IL-11 neutralizing antibody could partially reverse the promoting effect of miR-124 inhibitor on the bone metastasis and lung metastasis of breast cancer cells in mice." (PMID 29343249, 2018). "Indeed, IL-11 expression was negatively correlated with miR-124 expression in paired primary breast cancer tissues and adjacent non-tumorous mammary tissues as well as bone metastases from the breast cancer." (PMID 29343249, 2018). "Consequently, miR-124 and IL-11 might be new therapeutic targets and prognostic markers for breast cancer patients at early stage and at advanced stage with bone metastasis." (PMID 29343249, 2018). "However, inhibition of STAT3 abrogates Ras-induced IL-11 transcription in breast cancer." (PMID 28856117, 2017). "Other miRNAs recently implicated in breast cancer include miR-100, shown to target SMARCA5, SMARCD1, and BMPR2 genes, which directly influence tumor cell proliferation, and miR-30c, known to target TWF1 and IL-11, both of which are expressed in the MaSC/basal lineage." (PMID 26080807, 2015). "Our data indicate that a) IL-11 plays an important role in osteoclastogenesis by stimulating the development and/or survival of osteoclast progenitor cells and b) breast cancer may promote osteolysis in part by increasing the pool of osteoclast progenitor cells via tumor cell-derived IL-11." (PMID 23311882, 2013). "iCAF have been identified in several cancer types included in the PCFA (including PDAC and breast cancer), yet the iCAF population identified in HNSCC (IL11 + CAF) was restricted to HNSCC and GI cancers." (PMID 39757146, 2025). "The group then moved on to culture MCF-7 breast cancer cells with OSM, IL-10, IL-11, or growth differentiation factor 5 (GDF5) rich serum." (PMID 39123444, 2024). "By comparing gene expression between different sublines of human breast cancer cell line MDA-MB-122, researchers identified four highly overexpressed genes in the bone metastasis group: IL11, CTGF, CXCR4, and MMP-1." (PMID 38041134, 2023). "In the bone-specific metastatic breast cancer cell line MDA-MB-231, ectopic IL-11 expression interacts with overexpression of the chemokine receptor CXC motif chemokine receptor type 4 (CXCR4) to drive osteolytic metastasis." (PMID 37199584, 2023).
breast cancer (continued). "RANK is also expressed in breast cancer cells, and RANKL promotes the expression of bone metastasis-related genes (such as IL-11, NCF2, PRG-1, MMP-1) in RANK-positive tumor cells." (PMID 38041134, 2023). "Cyclooxygenase-2 (COX-2)-mediated production of IL-11 in poorly metastatic (MCF-7) and highly metastatic (MDA-MB231) breast cancer cell lines are necessary for osteolytic bone metastases to occur from breast cancer." (PMID 37199584, 2023). "This review will focus on the role of IL-6 and IL-11, in particular, in driving increased STAT3 transcriptional activity in breast cancer, and how this leads to metastasis and immune evasion within the tumor microenvironment." (PMID 35053592, 2022). "The majority of breast cancer metastases are lytic; breast cancer cells produce TNF-A, IL-8, IL-11, IGF1, LIF (leukemia inhibitory factor), lysyl oxidase, RANK ligands, and PTHrP." (PMID 36230523, 2022). "In breast cancer, the most studied members of this family are interleukin-6 (IL-6), leukemia inhibitory factor (LIF), oncostatin M (OSM), and interleukin-11 (IL-11)." (PMID 35163731, 2022). "Specifically, IL-6, IL-11, their receptors and downstream transcription factor STAT3, are known to be highly expressed in breast cancer, and the role of cytokine-induced STAT3 signaling in the breast tumor microenvironment is multifaceted." (PMID 35053592, 2022). "The authors suggest reduced expression of Runx2 and related target genes, including IL-11, MMP13, and PThrP, in breast cancer cells in the presence of miR-135 and miR-203 as a working mechanism." (PMID 35158995, 2022). "The literature and clinical study evidence highlight a clear role for IL-6 and IL-11-induced STAT3 activation in driving pro-tumorigenic processes and metastatic dissemination in all types of breast cancer." (PMID 35053592, 2022). "In breast cancer, MKL1 together with SRF promotes the expression of IL-11 to enhance breast cancer stemness and metastasis." (PMID 33500406, 2021). "According to previous studies, CITED2 regulates the expression of several growth factors such as transforming growth factor-beta (TGFβ), interleukin 11 (IL-11), interleukin 1 beta (IL-1β) and HIF-1α to promote breast cancer progression." (PMID 34569432, 2021). "The authors demonstrated that miR-30c regulates breast cancer chemoresistance and EMT by direct targeting of the cytoskeleton gene TWF1 and thus by indirect targeting of the cytokine IL-11." (PMID 34201209, 2021). "Here we show that direct application of LIV to human breast cancer cells reduced expression and secretion of RANKL and IL-11." (PMID 33298883, 2020). "After the colonization of DTCs, bone-derived TGF-β stimulates breast cancer cells to synthesize PTHrP, prostaglandin E2 (PGE2), IL-1, IL-6, and IL-11." (PMID 32117996, 2020). "Recombinant IL-11 is approved by the FDA to treat thrombocytopenia following radiation treatment in humans, and is commonly prescribed to breast cancer patients." (PMID 32765502, 2020). "In the tumor microenvironment, cancer cells coexist with preosteoclasts and release many soluble factors such as IL8, IL11, MMP1, MMP2, TNFα, and PGE2, which determine the direct osteolytic capability of breast cancer cells." (PMID 30126457, 2018). "To confirm the role of CXCL8 and IL11 in CUL1 regulated breast cancer cell migration and angiogenesis, we performed CXCL8 and IL11 rescue assays." (PMID 30578411, 2018). "Thus, the identification of a dysregulated miR-124/IL-11 axis helps elucidate mechanisms of breast cancer metastases to bone, uncovers new prognostic markers, and facilitates the development of novel therapeutic targets to treat and even prevent bone metastases of breast cancer." (PMID 29343249, 2018). "For example, the TGFβ-Smad pathway induces the expression of interleukin-11 (IL-11), connective tissue growth factor (CTGF), angiopoietin-like 4 (ANGPTL4), and cut-like homeobox 1 (CUTL1) to promote breast cancer invasion and metastasis." (PMID 28356139, 2017).
breast cancer (continued). "And it was found that miR-30c significantly suppressed lung metastases of breast cancer cells by targeting TWF1 and regulating IL-11-pSTAT3 signaling pathway in vivo." (PMID 29100303, 2017). "Some cytokines and growth factors (IL-1, IL-6, IL-11, TGF-β, and VEGF) stimulate the proliferation and invasion of breast cancer cells, whereas others (IL-12, IL-18, and IFN) suppress breast cancer progression." (PMID 27484639, 2016). "We extended our analysis to a breast cancer cell line, MDA-231, and observed that BHLHE41 induced IL-11 up-regulation, and BIRC3 and EDN2 down-regulation." (PMID 27384883, 2016). "Since STAT3 can be activated by a variety of cytokines, including IL-11, CNTF, LIF and G-CSF, in breast cancer, it is crucial to identify those tumors that depend on IL-6." (PMID 27602583, 2016). "Animal studies suggested that breast cancer cells expressing OPN have higher prevalence to BM, particularly if they coexpress IL-11, another potent osteolytic factor." (PMID 26062800, 2015). "IL-11 and granulocyte macrophage-colony stimulating factor (GM-CSF) are target genes of Runx2/CBFβ as OCL activators in breast cancer cells." (PMID 25147739, 2014). "CTGF and IL-11 are targets of TGF-β signaling, and their increased expression in breast cancer MDA-MB-231 cell line results in enhanced osteolytic bone metastases." (PMID 25147739, 2014). "Importantly, these findings have not only provided a better understanding of the role of IL-11 in breast cancer bone metastasis but also laid a foundation for future investigations to address therapeutic targeting of IL-11 for treating and preventing breast cancer induced osteolysis." (PMID 23311882, 2013). "The aim of this study was to elucidate the role of miRNAs in the bone metastatic process of breast cancer and specifically, to identify miRNAs that regulate TGF-β-induced IL-11 expression." (PMID 22629385, 2012). "In fact, expression of IL-11 and OPN by breast cancer cells has been found to be critical for the osteolytic activity of breast cancer cells." (PMID 22295244, 2012). "Triple‐negative breast cancer cells express high levels of interleukin‐11 (IL‐11) that can form complexes with soluble IL‐11 receptor (sIL‐11R)." (PMID 41178513, 2026). "The identification of IL-11, as well as of MMP-1 and MMP-13, which are also mediators of breast cancer metastasis to the bone, supports the hypothesis that PKD2 and PKD3 contribute, via the secretome, to the colonization of the bone in TNBC." (PMID 38323010, 2024). "Negative correlations between the IL11 expression levels and overall survival, disease specific survival and progression free survival were observed in breast cancer patients." (PMID 37153732, 2023). "A negative correlation between the piR-2158 and IL11 levels was observed in the tumors we collected from breast cancer patients." (PMID 37153732, 2023). "In breast cancer, DGUOK-AS1 may operate as a tumor promoter via modulating the miR-204-5p/IL-11 axis." (PMID 35178091, 2022). "In breast cancer, the novel lncRNA DGUOK-AS1 was identified to promote cancer progression and bone metastasis by decreasing tumor suppressor miR-204-5p and stimulating the secretion of IL-11." (PMID 35994202, 2022). "The activation of the IL-6 and IL-11-dependent signaling cascade leads to the phosphorylation of STAT3 to transcriptionally activate genes and pathways that promote breast cancer proliferation, suppress apoptosis, allow for immune evasion leading to metastatic growth, and attain chemoresistance." (PMID 35053592, 2022). "Similarly, hsa-miR-206, which inhibits self-renewal and invasiveness of breast cancer cells, also targets TWF1, which enhances MKL1 and SRF that in turn, promoting IL-11 expression." (PMID 35163731, 2022). "In breast cancer patients, a positive correlation between IL-11 and NRF2 has been detected, although this association has not been detected in cultured breast cancer cells." (PMID 35163731, 2022).
breast cancer (continued). "Although the molecular mechanism by which GPR81 regulates IL-6 and IL-11 expression remains unclear, it is plausible that lactate controls the production of these cytokines through GPR81 in breast cancer cells." (PMID 35428832, 2022). "In breast cancer, a minor subpopulation of cells expressing IL-11 can stimulate the growth of other cancer cells through a non-cell-autonomous manner." (PMID 34618689, 2021). "Further, IL-11 alone stimulates the recovery of platelets after radiation therapy, in mice, and its recombinant version has been approved by the FDA to treat radiation-induced thrombocytopenia in tumour patients (e.g., breast cancer)." (PMID 34201209, 2021). "Breast cancer with bone metastasis shows significantly increased expression of IL-11 in comparison with breast cancer without bone metastasis, and IL-11 is known to be involved in bone metastasis through the gp130/STAT3 pathway." (PMID 32674405, 2020). "Moreover, metastatic breast cancer cells express factors, such as parathyroid hormone-related peptide (PTHrP) that induces osteoblasts to produce mediators (RANKL, PGE, IL-11), which subsequently stimulate osteoclast differentiation from monocyte precursors." (PMID 30126457, 2018). "Therefore, elucidation of the molecular mechanism by which IL-11 increases osteoclastogenesis and bone resorption in breast cancer bone metastasis may help guide development of effective drugs and/or therapeutic regimens for preventing and treating breast cancer-induced osteolysis." (PMID 23311882, 2013). "While miR-379 has been shown to regulate IL-11 production in breast cancer cell lines, there have been no previous reports regarding expression levels in breast tissues." (PMID 23874748, 2013). "SPP1 when expressed with IL11 has been shown to promote metastasis of breast cancer cells to the bone but not to the adrenal medulla." (PMID 17430594, 2007). "Furthermore, breast cancer patients have substantially elevated NRF2 and IL-11 levels." (PMID 40584290, 2025). "Finally, survival analysis of breast cancer patients indicated that expression of both MAFF and BACH1 or MAFF, BACH1, and IL11 was significantly correlated with distant metastasis-free survival, further strengthening the prognostic significance of MAFF/IL11 pathways." (PMID 34262028, 2021). "Some of these cytokines, such as IL-1, IL-6, IL-11, and transforming growth factor (TGF)-β, stimulate breast cancer proliferation and invasion, whereas other cytokines such as IL-12p70, IL-18, and IFNs exert opposite effects on breast cancer proliferation or invasion." (PMID 32703187, 2020). "As a functional downstream miR-124 target, IL-11 protein expression detected by IHC analysis was enhanced in the primary breast cancer compared to paired non-tumor tissues and was further elevated in metastatic bone tissues as opposed to the miR-124 expression in human tissues." (PMID 29343249, 2018). "IL-11, a pleiotropic cytokine of the interleukin-6 type family, has been chosen as the “indicator” gene to investigate down-stream TGF-β signaling pathways, as reported for lung fibroblasts, periodontal ligament and gingival fibroblasts, and bone metastatic breast cancer cells." (PMID 25197981, 2014). "Also, IL-11 did not produce protective effects on the breast cancer tissue in this rat model of mucositis further highlighting its efficacy and safety upon administrating an effective dose." (PMID 22973511, 2012). "PiR-2158 significantly decreased the protein levels of IL-11 and phosphorylated STAT3 in mammary tumors, but did not change the levels of total STAT3." (PMID 37153732, 2023). "In this study, the presence of EBV and HPV in breast cancer significantly increased expression of the pro-carcinogenic factors, TGF-β and IL-6 (and IL-6-related IL-11) in breast tissue compared with viral-negative tissue." (PMID 32458652, 2020).